NLGN2 (neuroligin 2)
Diseases named in the same sentence as NLGN2 in open-access papers (continued):
Sharing a sentence is not in itself a finding about the gene and the disease.
schizophrenia (17 papers, 2013 to 2024). A major psychotic disorder characterized by abnormalities in the perception or expression of reality. "At the same time, variants of the paralogous NLGN2 gene have been identified as risk variants in schizophrenia due to their role as cell-adhesion molecules in post-synaptic membrane." (PMID 38573526, 2024). "In humans, Plscr3 and Sar1b are linked to obesity and lipid metabolic disease, respectively, Kif21a is linked to ocular disease, and Nlgn2 is linked to schizophrenia (MGI)." (PMID 38968323, 2024). "The most well-characterized NLGN2 variant was identified in a genetic screen of a cohort of schizophrenia patients in Taiwan, which identified four NLGN2 missense variants (p.R215H, p.V510M, p.R621H, p.A637T) that were not present in controls." (PMID 39766868, 2024). "In the present study, we sought to determine how the schizophrenia- and autism-associated synaptic adhesion proteins Nlgn2 and MDGAs functionally interact in vivo to regulate GABAergic synapses." (PMID 39284869, 2024). "Our functional analysis identified the NLGN2R309Q mutant as a loss-of-function, supporting our previous findings of the association of rare missense mutations in NLGN2 with schizophrenia." (PMID 33343614, 2020). "Intriguingly, a similar dysfunctional phenotype correlating with misfolding has been reported for the P89L variant of NLGN1 and the R215H variant of NLGN2, which are associated with autism and schizophrenia, respectively." (PMID 32873342, 2020). "In the present study, we generated a unique mouse model carrying a single point mutation R215H of NLGN2 gene that was originally identified from human schizophrenia patients." (PMID 29859117, 2018). "We have previously identified from schizophrenia patients a loss-of-function mutation Arg215→His215 (R215H) of neuroligin 2 (NLGN2) gene, which encodes a cell adhesion molecule critical for GABAergic synapse formation and function." (PMID 29859117, 2018). "In our previous study, we systematically screened for mutations in exon and promoter regions of NLGN2 in a sample of patients with schizophrenia." (PMID 29230184, 2017). "Interestingly, promotion of IGSF9B for inhibitory synapses development is coupled with NLGN2, loss of function variants of which were found in autism and schizophrenia patients." (PMID 33795679, 2021). "We have previously reported several novel mutations of NLGN2 from schizophrenia patients." (PMID 29859117, 2018). "We previously identified a missense mutation R215H of the NLGN2 in a patient with schizophrenia." (PMID 29230184, 2017). "Because cholinergic impairments are implicated in schizophrenia, NLGN2 dysfunction in cholinergic synapses may also contribute to the pathophysiology in these subjects." (PMID 24039767, 2013). "Mutations of NLGN2 gene were recently identified in schizophrenia patients." (PMID 24039767, 2013). "Taken together, these findings suggest that NLGN2 and NLGN3 mutations are part of the genetic underpinnings of schizophrenia and support the implication of synaptic dysfunction in schizophrenia pathogenesis." (PMID 33343614, 2020). "Missense mutations in NLGN2 or NLGN3 have been associated with several neuropsychiatric diseases, such as schizophrenia and autism." (PMID 33343614, 2020). "NLGN2 overexpression in schizophrenia neurons rescued synaptic puncta deficits while NLGN2 knockdown in healthy neurons resulted in reduced synaptic puncta density." (PMID 31780643, 2019). "The antioxidant N-acetylcysteine increased the nuclear area in schizophrenia interneurons, increased NLGN2 expression and rescued synaptic deficits." (PMID 31780643, 2019). "Accordingly, our results highlight NLGN-2 as a relevant target for future preclinical studies that combine animal models of neurodevelopmental disorders (eg, autism, schizophrenia) with early life stress." (PMID 26152839, 2016). "Mutations in NRXN1, NRXN2, NLGN2, NLGN4, and SHANK3 genes related to ASD have been also found in schizophrenia patients." (PMID 25780553, 2015).
schizophrenia (continued). "Some of the mutations of the genes related to ASD, including NRXN1, NRXN2, NLGN2, NLGN4, SHANK3, and SynGAP, have been also found in the schizophrenia patients; for instance, two de novo mutations (R1117X and R536W) were identified in the SHANK3 gene of two families of schizophrenia." (PMID 25780553, 2015). "Rare variation in NLGN2 has been identified in subjects with schizophrenia." (PMID 26793096, 2015).
autism (16 papers, 2013 to 2025). Persistent deficits in social interaction and communication and interaction as well as a markedly restricted repertoire of activity and interest as well as repetitive patterns of behavior. "In this study, we analysed the trans-synaptic interactions of alpha- and beta-Nrxn1 isoforms with Nlgn1 and Nlgn2 in cultured neurons and studied the type of association affected by mutant beta-Nrxn1 in a mouse model of autism." (PMID 40087687, 2025). "Mutations in Nlgn2 genes, leading to impaired folding and trafficking of Nlgn2, have been found in autism subjects." (PMID 38201218, 2023). "Individual mutations at these sites, either by expressing the phospho-null (NLGN2-S714A), phospho-mimic (NLGN2-S714D), or the analogous autism point mutation (NLGN2-R705C), still enhanced inhibitory responses comparable to full-length NLGN2." (PMID 27805570, 2016). "First, the NLGN2 gene previously was associated with autism and pervasive developmental disorders." (PMID 35887345, 2022). "Thus, it remains to be determined what molecules interact at this site and how this autism-associated mutation results in disruption of gephyrin binding to NLGN2." (PMID 27805570, 2016). "To determine whether this was the case, we made two more double mutants, combining either the autism mutation or phospho-null mutation with the point mutation in the gephyrin-binding domain that inhibits gephyrin binding (NLGN2-R705C-Y770A or NLGN2-S714A-Y770A)." (PMID 27805570, 2016). "The combined autism mutation and gephyrin-binding double point mutant (NLGN2-R705C-Y770A) exhibited enhancement comparable to full-length NLGN2, while the combined phospho-null mutation and gephyrin-binding double point mutant (NLGN2-S714A-Y770A) showed significantly reduced enhancement." (PMID 27805570, 2016). "However, when we expressed the double point mutant of the autism-associated mutation with the phospho-null mutation (NLGN2-R705C-S714A) the enhancement was dramatically reduced, suggesting that together these residues are critical for NLGN function at inhibitory synapses." (PMID 27805570, 2016). "High levels of jumping behavior have been reported in Shank2 null, Sh3rf2 haploinsufficient, Camk2a-E183V, and Nlgn2 overexpression mice that model genetic risk factors for ASD and in the C58 inbred strain described as a mouse model of autism." (PMID 35227461, 2022). "Nlgn2 is a synapse-specific adhesion protein that is known to interact with synaptic GABAAR subtypes and receptor scaffolds; dysfunction of this protein has been implicated in autism." (PMID 37108794, 2023). "We focused on two sites, a residue at R705 linked to an autism mutation previously found in NLGN4 that inhibited its function at excitatory synapses, and a putative phosphorylation site at S714 previously shown to affect gephyrin binding to NLGN2." (PMID 27805570, 2016). "Other autism-related mouse models have been shown to have interneuron subtype-specific effects including the Nlgn2 knockout mouse with impaired PV inhibitory transmission and the Fmr1 mouse model of Fragile X syndrome with impairments in both PV and SOM inhibitory networks." (PMID 26469287, 2015).
Cognitive impairment (4 papers, 2015 to 2022). Abnormal cognition is characterized by deficits in thinking, reasoning, or remembering. "Interestingly, loss of neuroligin-2 is linked to social dysfunction and cognitive impairment, deficits often found in preterm infants." (PMID 26388734, 2015).
depression (4 papers, 2018 to 2025). "Interestingly, we found that binding-deficient Nlgn2 mutations restricted to the LHb prevented the onset of depression in the Cre group following CRS, while the EGFP control mice exhibited depressive-like behaviors assessed by the TST, FST, and SPT." (PMID 39897557, 2025). "To probe whether the disruption of MDGA1 and Nlgn2 interactions in the LHb also alleviates chronic stress-mediated depression-related behaviors in mice, we generated transgenic mice with a conditional knock-in Nlgn2 mutation (Nlgn2mutflox/flox)." (PMID 39897557, 2025). "Behavioral measures of depression in Nlgn2 mutants revealed a marked reduction in depression indicators following CRS." (PMID 39897557, 2025). "Use of an MDGA1 binding deficient Nlgn2 genetic variant further confirmed the central regulatory role this complex (MDGA1/Nlgn2) plays in providing the molecular substrates for stress-mediated depression resilience." (PMID 39897557, 2025). "To explore these questions, we combined genetic manipulations of MDGA1/Nlgn2 with functional assessment of LHb synapses in mice subjected to restraint stress and subsequent biobehavioral assays for depression." (PMID 39897557, 2025). "Analysis of NLGN transcription genes in patients with death from severe depressive disorder suggested that the expression of NLGN2 was downregulated." (PMID 37786892, 2022). "Taken together, these results indicates that the interaction between MDGA1 and Nlgn2 in the LHb may play roles in the regulation of LHb function in the development of stress-induced depression." (PMID 39897557, 2025). "LHb neuronal responses to chemogenetic activation of the LH-LHb pathway or acute restraint stress were similarly muted in the Nlgn2mut/mut mice, confirming that decreased binding of MDGA1 to Nlgn2 is specifically required for conferring resistance to stress-induced depression." (PMID 39897557, 2025). "Finally, manipulating the expression MDGA1 or binding of MDGA1 to Nlgn2 can serve as a molecular tool for selectively modulating inhibitory synaptic drive in the LHb to prevent the onset of major depression following stress." (PMID 39897557, 2025). "Targeting MDGA1/Nlgn2 complexes residing at GABAergic synapses within the lateral habenula may be viable for alleviating core behavioral symptoms of major depression." (PMID 39897557, 2025). "The anxiolytic effects of IgSF9b deletion in Nlgn2 KO mice are intriguing in light of previous studies showing that variants in IgSF9b are associated with major depression and the negative (mainly affective) symptoms of schizophrenia." (PMID 30573727, 2018). "Elevated levels of MDGA1 within the LHb, further emphasizes the highly regional specificity of MDGA1 expression in the brain, which may add to the complexity of Nlgn2's regulation of mood related brain circuitry as well as provide specific drug target for depression." (PMID 39897557, 2025). "Given the essential role of the LHb in regulation of depression, we next assessed whether the expression patterns of MDGA1 and Nlgn2 were changed using a mouse model of chronic stress, which is a major risk factor for depression onset." (PMID 39897557, 2025).
breast carcinoma (2 papers, 2021 to 2024). "Moreover, NLGN2 overexpression in breast cancer was significantly associated with large tumor size, lymph node metastasis, late TNM stage, and high histological grade." (PMID 34804909, 2021). "We assessed the expression levels and prognostic values of NLGN2 in the open-access genome and proteome datasets of breast cancer, and validated the in-silico bioinformatics results with in-house patient tissue samples." (PMID 34804909, 2021). "Since the spatial distribution of a protein is a determinant of its function and mechanism, we further assessed the distribution of NLGN2 in breast cancer cells using the THPA database based on integrated multiple analyses." (PMID 34804909, 2021). "We also investigated the role of NLGN2 in the overall survival of patients with different breast cancer subtypes, its correlation with local immunomodulatory molecules and cells, as well as its intracellular localization." (PMID 34804909, 2021). "Since immune regulation is a key factor in cancer progression, we also analyzed the potential influence of NLGN2 on breast cancer immunity to better understand its prognostic role." (PMID 34804909, 2021). "In conclusion, NLGN2 has a prognostic role and immunoregulatory potential in breast cancer, and its functions likely have a mitochondrial basis." (PMID 34804909, 2021). "In this study, we analyzed the potential role of NLGN2 in breast cancer, which is under partial neuroendocrine neoplastic growth." (PMID 34804909, 2021). "Taken together, unlike the currently established breast cancer biomarkers, elevated NLGN2 indicates favorable prognosis for breast cancer patients with the basal, luminal A, and luminal B phenotypes." (PMID 34804909, 2021). "Given the relevance of tumor metastasis and pathological grading in the survival of breast cancer patients, we next analyzed the relationship between NLGN2 expression and the status of tumor lymph node metastasis or tumor grades." (PMID 34804909, 2021). "The relationship between NLGN2 expression and the clinicopathological features of breast cancer patients." (PMID 34804909, 2021). "NLGN2 was identified as a prognostic factor in breast cancer subtypes, and its high expression correlated to a favorable survival outcome." (PMID 34804909, 2021). "The aim of this study was to determine the clinical relevance and prognostic value of NLGN2 in breast cancer." (PMID 34804909, 2021). "Of note, we concluded the immunological relevance of NLGN2 in breast cancer solely through immunohistochemical staining of CD3+ and CD8+ T cells in the tumor tissues." (PMID 34804909, 2021). "To validate the in-silico prognostic data of NLGN2 in breast cancer, we next analyzed its in-situ expression levels in patient tissue samples by IHC staining." (PMID 34804909, 2021). "Through in-silico assessment and further validation, we found here that the neuronal protein NLGN2 has significant clinical relevance and prognostic value in breast cancer." (PMID 34804909, 2021). "The prognostic role of NLGN2 may be attributed to its mitochondrial location, and the mechanism warrants further investigation to consider NLGN2-targeted therapeutic strategy against breast cancer." (PMID 34804909, 2021). "We therefore hypothesize that the mitochondrial localization of NLGN2 is instrumental to its prognostic role in breast cancer, and should be explored further, especially from the perspectives of immunoregulation and immunotherapy." (PMID 34804909, 2021). "To further determine the clinical pertinence of NLGN2 in breast cancer, we assessed its prognostic performance in different intrinsic subtypes with or without the estrogen receptor (ER), progesterone receptor (PR) and Erb-B2 receptor tyrosine kinase 2 (HER2) expression." (PMID 34804909, 2021).
breast carcinoma (continued). "Taken together, these findings indicated that NLGN2 might have an immune system-dependent role in breast cancer, and the prognostic significance of NLGN2 is likely due to its correlation with a favorable immune signature." (PMID 34804909, 2021). "Interestingly, NLGN2 expression was predominantly localized in the mitochondria of the MCF7 breast cancer cell line." (PMID 34804909, 2021). "Similarly, NLGN2 was reported to be a prognostic marker in breast cancer." (PMID 38413734, 2024). "Thus, the upregulation of NLGN2 is associated with better prognosis in HER2- breast cancer as opposed to other molecular subtypes." (PMID 34804909, 2021). "Furthermore, NLGN2 was predominantly localized in the mitochondria of breast cancer cells." (PMID 34804909, 2021). "Taken together, NLGN2 expression correlates to the metastasis of breast cancer as opposed to pathological grading." (PMID 34804909, 2021). "In contrast, higher expression of NLGN2 was not conductive to the survival of the HER2+ breast cancer patients (HR, 0.59; 95%CI, 0.5 to 0.69; p > 0.05)." (PMID 34804909, 2021).
diabetes (2 papers, 2022 to 2024). "This idea is supported by the results of studies focusing on the role of NLGN2 in insulin secretion and on the potential of NLGN2 mimetics as tools for treating patients with diabetes." (PMID 38413734, 2024). "In our studies, the expression levels of NLGN2 and NLGN3 were elevated in the maternal diabetes-related streptozotocin-induced ASD mouse model, which may be a response to the increased oxidative stress." (PMID 36479216, 2022).
epilepsy (2 papers, 2024 to 2025). A brain disorder characterized by episodes of abnormally increased neuronal discharge resulting in transient episodes of sensory or motor neurological dysfunction, or psychic dysfunction. "Similarly, Ank3-exon1b knockout (Ank3-1b KO) mice, a model relevant to epilepsy, also exhibited a higher prevalence of seizures during REM sleep, and Nlgn2 KO mice also showed abnormal EEG events that predominated during wakefulness and REM sleep." (PMID 41408339, 2025).
fragile X syndrome (2 papers, 2015 to 2023). A genetic syndrome caused by mutations in the FMR1 gene which is responsible for the expression of the fragile X mental retardation 1 protein. "Translation of the mRNAs for NLGN1, NLGN2, and NLGN3 is negatively regulated by Fragile X mental retardation protein (FMRP), loss of this translational repressor, FMRP, leads to Fragile X syndrome, associated with ASD." (PMID 37807632, 2023).
Intellectual disability (2 papers, 2015 to 2019). "A 17p13.1 duplication that harbors the NLGN2 gene has been observed in individuals with intellectual disability." (PMID 26793096, 2015).
absence seizures (1 paper, 2020). "In this study, we show that Neuroligin 2 (NLG2) knockout mice exhibit abnormal spike and wave discharges (SWDs) and behavioral arrests characteristic of absence seizures." (PMID 32719346, 2020).
ADNP syndrome (1 paper, 2020). "ADNP showed relatively reduced expression in the ADNP syndrome cerebellum, which was also observed for 25 additional genes (representing >50% of the tested genes), including NLGN1, NLGN2, PAX6, SMARCA4, and SNAP25, converging on nervous system development and tauopathy." (PMID 32661233, 2020).
breast tumors (1 paper, 2021). "NLGN2 expression level in breast tumors is associated with molecular subtypes, metastatic statues, immunomodulatory signatures and lymphocyte infiltration." (PMID 34804909, 2021). "NLGN2 is upregulated in breast tumor tissues and correlates with higher survival rates." (PMID 34804909, 2021).
cerebral infarction (1 paper, 2025). An ischemic condition of the brain, producing a persistent focal neurological deficit in the area of distribution of the cerebral arteries. "We further analyzed the expression differences of Pip5k1c, Nlgn2, Fzd2, Cd86, Agpat1, and Degs2 between the cerebral infarction at 3, 6, and 12 h and the control group." (PMID 40520774, 2025). "The AUC values of Pip5k1c, Nlgn2, Fzd2, Cd86, Agpat1, and Degs2 were all 1, suggesting that Pip5k1c, Nlgn2, Fzd2, Cd86, Agpat1, and Degs2 have good sensitivity and specificity for the diagnosis of cerebral infarction." (PMID 40520774, 2025).
developmental delay (1 paper, 2024). "The expression levels of other genes associated with developmental delay (FOXG2, NLGN2, and MSI1) peaked later in the lineage." (PMID 39363111, 2024).
HIV-1 infection (1 paper, 2020). The type species of lentivirus and the etiologic agent of acquired immunodeficiency syndrome (AIDS). "miR-7 from astrocytes can cause the downregulation of neuronal neuroligin 2 (NLGN2) and ultimately lead to synaptic alterations after HIV-1 infection." (PMID 32192523, 2020).